OSMR (oncostatin M receptor)
Description:
Functions as a shared membrane-bound signal-transducing subunit in two distinct receptor complexes, the type II OSM receptor (heterodimer composed of OSMR and IL6ST) and the IL31 receptor complex (heterodimer composed of OSMR and IL31RA) which respectively bind OSM and IL31. Functionally, OSM signaling via OSMR/IL6ST regulates many processes including cell proliferation, cell differentiation, cytokine production, whereas the IL31 signaling via OSMR/IL31RA is particularly important in skin immunity. Mechanistically, in both the OSM-IL6ST/gp130-OSMR and IL31-IL31RA-OSMR complexes, receptor dimerization activates JAK1 and JAK2 (and to a lesser extent TYK2) associated with the intracellular domains of IL6ST/gp130 and OSMR (or IL31RA and OSMR). These kinases phosphorylate tyrosine residues on IL6ST/gp130 and OSMR (or IL31RA and OSMR), creating docking sites for STAT1, STAT3, and STAT5B, which are then phosphorylated and activated. In addition, the IL31 receptor complex activates the MAPK pathway (MAPK3/ERK1-MAPK1/ERK2) via recruitment of the adapter protein SHC1.
Synonyms: OSMRbeta; IL-31R-beta; IL-31RB; OSMRB; PLCA1
Tractability: Antibody: a drug acting on it is in phase 2 or 3 trials; its Gene Ontology location is reachable by antibodies, with high confidence; UniProt predicts a signal peptide or a membrane-spanning region. PROTAC: ubiquitination databases record sites on it.
Gene: Protein-coding gene on chromosome 5 (38,845,852 to 38,945,596, forward strand). Ensembl gene ENSG00000145623.
Subcellular location: Membrane
Subcellular location (Human Protein Atlas): Nucleoli
Pathways (Reactome):
Immune System: IL-6-type cytokine receptor ligand interactions
Gene Ontology:
Molecular function: coreceptor activity; growth factor binding; oncostatin-M receptor activity; protein binding; ciliary neurotrophic factor receptor binding; cytokine binding; cytokine receptor activity
Biological process: cytokine-mediated signaling pathway; oncostatin-M-mediated signaling pathway; positive regulation of cell population proliferation; response to cytokine; positive regulation of acute inflammatory response
Cellular component: apical plasma membrane; oncostatin-M receptor complex; plasma membrane; external side of plasma membrane; receptor complex; membrane
Genetic constraint (gnomAD): Loss-of-function variants: 75 observed, 98.05 expected, observed/expected ratio (o/e) 0.76, 90% interval 0.63 to 0.93. The upper end of that interval is the gene's LOEUF score, 0.93, which puts it in group 3 of 6, group 1 being the genes least tolerant of losing a copy. Missense variants: 1,080 observed, 1,192.7 expected, observed/expected ratio (o/e) 0.91, 90% interval 0.86 to 0.95. Synonymous variants: 400 observed, 425.36 expected, observed/expected ratio (o/e) 0.94, 90% interval 0.87 to 1.02.
Homologues: Orthologues: chimpanzee OSMR (99% identical), macaque OSMR (95% identical), pig OSMR (72% identical), dog OSMR (72% identical), rabbit OSMR (68% identical), guinea pig OSMR (61% identical), rat Osmr (56% identical), mouse Osmr (55% identical), zebrafish lifra (23% identical), zebrafish lifrb (21% identical), zebrafish ghra (7% identical), zebrafish ghrb (6% identical), and 2 more. Paralogues in human: LIFR (28% identical), IL12RB2 (15% identical), IL6ST (15% identical), CSF3R (13% identical), IL31RA (12% identical), LEPR (11% identical), IL27RA (10% identical), IL12RB1 (8% identical), IL23R (8% identical), PRLR (8% identical), CRLF1 (7% identical), GHR (7% identical), and 11 more.
Diseases named in the same sentence as OSMR in open-access papers:
OSMR is named in the same sentence as 113 diseases in open-access papers, as found by Europe PMC text mining. Sharing a sentence is not in itself a finding about the gene and the disease. The quoted sentences say what the papers report.
glioblastoma (18 papers, 2016 to 2025). The most malignant astrocytic tumor (WHO grade IV). "More importantly, we established that loss of OSMR sensitizes the response of glioblastoma tumors to IR therapy." (PMID 32807793, 2020). "In vivo experiments, we also injected OSMR‐overexpressing GL261 cells into a mouse model to simulate glioblastoma tumor formation." (PMID 39815665, 2025). "Applying Reboot on data from 154 glioblastoma patients, we identified a three-gene signature (IKBIP, OSMR, PODNL1) whose increased derived risk score was significantly associated with worse patients’ prognosis." (PMID 34316711, 2021). "used bioinformatics to identify four survival-associated differentially expressed genes (OSMR, HOXC10, SCARA3, and SLC39A10) in glioblastomas and found that glioblastoma patients with abnormal HOXC10 expression had poor survival outcomes." (PMID 34113572, 2021). "We found that in a variety of tumors such as pancreatic ductal adenocarcinoma, glioblastoma, and colorectal cancer, OSMR is highly expressed, and OSMR can regulate cell proliferation and tumor growth." (PMID 34422217, 2021). "Our data suggest that OSMR targeting in combination with IR provides a promising therapeutic approach for better treatment of glioblastoma tumors." (PMID 32807793, 2020). "OSMR forms a co-receptor complex with EGFRvIII to amplify receptor tyrosine kinase signalling and glioblastoma tumorigenesis." (PMID 32807793, 2020). "The expression of OSMR is upregulated in mesenchymal and classical glioblastoma subtypes and upregulation of OSMR correlates significantly with poor patient prognosis." (PMID 32807793, 2020). "OSMR forms a complex with EGFRvIII, the most common EGFR mutation that occurs in glioblastoma, and regulates glioblastoma tumour growth." (PMID 30382873, 2018). "High expression of OSMR was observed in glioblastoma, especially in the mesenchymal subtype, and was regarded as a prognostic risk factor." (PMID 27023521, 2016). "Importantly, deletion of OSMR is sufficient to sensitize the response of glioblastoma tumors to IR therapy and to prolong lifespan." (PMID 32807793, 2020). "The suppression of the receptor for oncostatin M (OSMR) can prevent glioblastoma cell growth." (PMID 32807793, 2020). "We identified oncostatin M receptor (OSMR) as a key ANXA2 target gene in GBM utilizing microarray analysis and hierarchical clustering analysis of the Ivy Glioblastoma Atlas Project and The Cancer Genome Atlas datasets." (PMID 32248843, 2020). "Moreover, in glioblastoma cells, OSMR serves as an essential co-receptor for EGFRvIII—a truncated, active form of epidermal growth factor receptor—and its silencing or pharmacological inhibition of the EGFRvIII-OSMR interaction suppressed Stat3 activation, cell proliferation, and tumor growth." (PMID 35163735, 2022). "ANXA2 was shown to regulate OSMR expression via STAT3 phosphorylation, resulting in the shift of glioblastoma cells towards a mesenchymal phenotype with a prominent proliferative capability." (PMID 33712571, 2021). "In the present study, we report the discovery of a mitochondrial OSMR that functions to promote OXPHOS and confers resistance of glioblastoma tumors to IR." (PMID 32807793, 2020). "The cytokine receptor for oncostatin M (OSMR) regulates BTSC proliferation and glioblastoma tumorigenesis." (PMID 32807793, 2020). "Among the genes in this model, OSMR and SOX21 have been previously reported in glioblastoma studies." (PMID 30382873, 2018). "Similarly, Oncostatin M receptor (gene: OSMR), a member of the type I cytokine receptor family, functions as a co-receptor for EGFR and enhanced EGFR signaling in glioblastoma." (PMID 39995668, 2025). "OSMR was previously shown to be expressed by inflammatory fibroblasts and its activation in malignant cells promotes EMT in breast cancer and pancreatic cancer and a mesenchymal state in glioblastoma." (PMID 41384492, 2025).
glioblastoma (continued). "OSMR is a cell surface receptor that is a key component of EGFRvIII-STAT3 signaling, which forms a feedforward signaling mechanism with these molecules to drive glioblastoma genesis and progression." (PMID 37538176, 2023). "OSMR, characterized as a novel key regulator of glioblastoma tumorigenesis through EGFRvIII-STAT3 signaling, also correlates with poor prognosis in GBM patients both independently and also as part of a 4-gene signature." (PMID 34316711, 2021). "Gene expression profiling using RNA-Seq analyses of OSMR and EGFRvIII in mouse astrocytes revelated two gene sets: OSMR/EGFRvIII common and OSMR unique candidate target genes that were not shared by EGFRvIII20, suggesting that OSMR may regulate glioblastoma tumorigenesis via additional mechanisms." (PMID 32807793, 2020).
breast cancer (15 papers, 2013 to 2025). A primary or metastatic malignant neoplasm involving the breast. "The cell population showing the most significant association with OSMR expression in human breast cancer samples is the CAF compartment, and our data point to an important role for this cell type in transducing OSM signaling within the TME." (PMID 35192545, 2022). "While OSM has historically been identified as an inhibitor of breast cancer proliferation, overexpression of OSM and OSMRβ has been linked to decreased overall survival, decreased reoccurrence-free survival and decreased metastasis free survival in breast cancer patients." (PMID 37841259, 2023). "Furthermore, high expression of OSM and its receptor (OSMR) was associated with poor prognosis for breast cancer patients." (PMID 35163731, 2022). "Interestingly, OSMR expression was associated with shorter recurrence-free survival and overall survival in breast cancer patients, suggesting a connection to disease progression in breast cancer." (PMID 32023849, 2020). "TIMER analysis showed that OSMR mRNA expression significantly correlates with fibroblast enrichment in human breast cancer, while OSM mRNA levels show the most significant associations with myeloid macrophage and neutrophil populations." (PMID 35192545, 2022). "High OSM receptor (OSMR) expression in clinical samples of glioblastoma, breast cancer, and cervical cancer correlates with decreased survival in those patients." (PMID 35192545, 2022). "Conversely, OSMR was only detected by RT-qPCR in breast cancer cells and fibroblasts, showing significantly higher expression in fibroblasts compared with epithelial cells." (PMID 35192545, 2022). "In other solid cancers such as breast cancer and squamous cell carcinoma, OSMR is directly expressed by the tumour cells and regulates cancer stem cell properties, EMT and metastasis." (PMID 34921158, 2021). "In the context of OSM/OSMR signaling, high levels of OSM and OSMR mRNA expression were associated with low expression of ESR1 (ER) and ER-regulated genes in a breast cancer gene expression data set." (PMID 32023849, 2020). "We found that the expression of OSM and its receptor (OSMR) were significantly higher in ER-negative/HER2-negative compared with that of luminal/HER2-positive breast cancers (OSM, p = 3.90 × 10−2; OSMR, p = 2.80 × 10−3)." (PMID 28106823, 2017). "Stromal OSM/OSMRβ has recently been shown to play a distinct role in breast cancer progression." (PMID 37841259, 2023). "OSM receptor (OSMR) deletion in a multistage breast cancer model halted tumor progression." (PMID 35192545, 2022). "However, our results reveal a key aspect of OSM/OSMR signaling that is instrumental for breast cancer progression beyond the epithelial compartment." (PMID 35192545, 2022). "Conversely, OSMR downregulation by shRNA in CAF-173 delayed tumor onset and tumor growth at early stages when coinjected with MDA-MB-231 breast cancer cells ectopically expressing human OSM (MDA-MB-231-hOSM)." (PMID 35192545, 2022). "Nonetheless, OSMRβ overexpression may be a potential clinical marker for cervical cancer patients, HER2 in breast cancer, and an anti-OSMRβ monoclonal antibody could improve outcome for patients with cervical cancer." (PMID 37841259, 2023). "Loss of OSMR in the nontumoral tissue hampers tumor aggressiveness, thus demonstrating that tumor cell–extrinsic OSM signaling is a pivotal factor in breast cancer progression." (PMID 35192545, 2022). "OSMR is a strong candidate for antibody-mediated inhibition, a strategy that has had a major impact on haematological malignancies and various solid tumours such as HER2-positive breast cancers." (PMID 24659184, 2014). "Furthermore, OSM and OSMR are upregulated in response to STAT3 activation and the signaling triggered by this cytokine promoted the expression of metalloproteinases MMP3, MMP12, and MMP14, that are relevant for remodeling normal mammary tissue, but would also facilitate mammary tumor invasiveness." (PMID 35163731, 2022).
breast cancer (continued). "Since the status of OSMR on breast cancer cell lines has not been fully elucidated yet, the effects of OSM could be delineated between the expression and functionality of OSMR and LIFR in such cell lines." (PMID 32023849, 2020). "However, OSM can signal through both LIFR and OSMR to induce downstream signaling, and the function of OSM:LIFR and OSM:OSMR signaling in breast cancer cells has not been fully explored." (PMID 32023849, 2020).
glioma (13 papers, 2016 to 2025). A benign or malignant brain and spinal cord tumor that arises from glial cells (astrocytes, oligodendrocytes, ependymal cells). "Subsequently, using the EdU cell proliferation assay kit and colony formation assay, we assessed the impact of OSMR overexpression on glioma cell proliferation." (PMID 39815665, 2025). "First, by transfecting OSMR overexpression plasmids, we successfully elevated OSMR expression levels in glioma cells." (PMID 39815665, 2025). "Our results showed that FN1, ITGA5, OSMR, and NGFR were overexpressed in TCGA-GBM, suggesting that these genes were not only prognostic but also diagnostic between high-grade gliomas and normal brain tissue." (PMID 35954323, 2022). "Overexpression of OSM and OSMR has been detected in various cancers, including gastric, colorectal, breast, and glioma." (PMID 36193073, 2022). "We established that OSMR directly interacts with NDUFS1/NDUFS2 of complex I in the mitochondria of patient derived glioma stem cells." (PMID 32807793, 2020). "In the REMBRANDT dataset, we found that ANXA2 and OSMR expression were associated with the histopathologic grade of glioma, and higher expression was observed in GBM than in lower grade glioma." (PMID 32248843, 2020). "GSEA of the GSE4412 demonstrated a positive association between expression of hypoxia pathway signature genes and high ANXA2 or OSMR expression in glioma specimens." (PMID 32248843, 2020). "First, OSMR expression level is highly upregulated in high grade glioma and upregulation of OSMR is an important predictor of poor patient survival." (PMID 32807793, 2020). "Here, the authors demonstrate a role for OSMR in modulating glioma stem cell respiration and its impact on resistance to ionizing radiation." (PMID 32807793, 2020). "In support of this, GSEA of GSE4412 showed a positive association between expression of interleukin (IL) –6–JAK–STAT3 pathway signature genes and high ANXA2 or OSMR expression in human glioma specimens." (PMID 32248843, 2020). "In in vitro experiments, we established a stable GL261 glioma cell line overexpressing OSMR." (PMID 39815665, 2025). "We further elucidated the regulatory role of OSMR in the ferroptosis pathway in glioma." (PMID 39815665, 2025). "Importantly, we found that KD of OSMR in glioma stem cells generates excess ROS and induces cell death in vitro and in vivo." (PMID 32807793, 2020). "Additionally, histopathological analysis confirmed that the expression level of the proliferation marker Ki‐67 in tumor tissues was markedly increased, which was consistent with the in vitro results, indicating that OSMR overexpression enhanced the proliferative capacity of glioma cells." (PMID 39815665, 2025). "In order to elucidate the role of OSMR in regulating immune responses, we utilized two in situ mouse models using GL261 mouse glioma cells." (PMID 39815665, 2025). "High expression of oncostatin M (OSM) receptor OSMR has recently emerged as a poor prognosis factor in several malignancies such as acute myeloblastic leukemia (AML), gliomas, pancreatic, gastric and kidney carcinomas." (PMID 41040517, 2025). "Macrophages can directly induce the MES phenotype transition of glioma cells via cytokine-mediated pathways, such as the secretion of oncostatin M (OSM) by macrophages, which activates OSMR on GBM cells and triggers the switch to the MES molecular subtype." (PMID 38398231, 2024). "Based on further validation using the Chinese Glioma Genome Atlas (CGGA) database, we identified FN1, ITGA5, OSMR, and NGFR as stiffness-dependent prognostic genes." (PMID 35954323, 2022). "After validation using the Chinese Glioma Genome Atlas (CGGA) database, we further identified four stiffness-dependent prognostic genes: FN1, ITGA5, OSMR, and NGFR." (PMID 35954323, 2022). "Four stiffness-dependent prognostic genes (FN1, ITGA5, OSMR, and NGFR) were identified from GSE158097 and TCGA glioma datasets using bioinformatics analysis." (PMID 35954323, 2022).
glioma (continued). "Previous studies have evaluated the role of OSMR and its ligand OSM in a range of cancers, including glioma." (PMID 32248843, 2020). "Finally, we assessed the clinical significance of ANXA2 and OSMR expression on tumor growth and patient prognosis by analyzing the REMBRANDT, TCGA, and Chinese Glioma Genome Atlas (CGGA) dataset." (PMID 32248843, 2020). "Due to the important roles of PD1, LARI1, and OSMR contributing to immunosuppressive microenvironment, we further examined the co-expression of LSP-1 and PD1, LARI1, and OSMR in clinical different grades glioma samples by IHC." (PMID 32003759, 2020). "Three genes closely related to glioma, RND3, OSMR, and CREB3L2, were significantly upregulated and might be the key factors in EBLN1 regulating the proliferation and apoptosis of OL cells." (PMID 27023521, 2016).
brain tumor (7 papers, 2019 to 2025). "Conversely, OSMR regulates the brain tumor stem cells’ proliferation via interacting with NADH ubiquinone, NADH ubiquinone oxidoreductase 1/2 (NDUFS1/2) of complex I to promote mitochondrial respiration, suggesting the dual role of this OSMR." (PMID 40843259, 2025). "The cytokine receptor for oncostatin M (OSMR) regulates self-renewing brain tumor stem cells and promotes the resistance of GBM to ionizing radiation." (PMID 33708242, 2021). "The OSMR (receptor for the cytokine Oncostatin M) is a regulator of brain tumor stem cells (BTSC) proliferation by mediating EGFR phosphorylation." (PMID 32725165, 2020). "Similarly, another study identified OSMR as a novel key regulator of brain tumor stem cell proliferation and GBM tumorigenesis (Mohan, Bonni, & Jahani‐Asl, 2017)." (PMID 30859746, 2019). "Studies targeting OSMRβ and STAT3 suggest that a clinical therapeutic that disrupts OSM/OSMRβ/STAT3 signaling can repress brain tumor growth and increase chemoresistance in aggressive brain tumors." (PMID 37841259, 2023). "EGFRvIII and OSMR are obligate co-receptors in maintaining oncogenic STAT3 signaling in mouse astrocytes and human brain tumor stem cells." (PMID 35954323, 2022). "In conclusion, our results established that KD of OSMR increases cellular ROS levels, promotes BTSC death, sensitizes the response of BTSCs and brain tumors to IR, and most importantly extends animal lifespan." (PMID 32807793, 2020).